RNU6-72P (RNA, U6 small nuclear 72, pseudogene)
Synonyms: LOC124902815; formerly RNU6-72
Gene: Small nuclear RNA gene on chromosome 11 (72,047,873 to 72,047,951, reverse strand). Ensembl gene ENSG00000207012.
Homologues: Orthologues: macaque U6 (95% identical), mouse Gm23428 (89% identical), pig U6 (78% identical), guinea pig U6 (66% identical). Paralogues in human: RNU6-732P (94% identical), RNU6-820P (94% identical), RNU6-12P (92% identical), RNU6-13P (92% identical), RNU6-16P (92% identical), RNU6-25P (92% identical), RNU6-271P (92% identical), RNU6-29P (92% identical), RNU6-32P (92% identical), RNU6-41P (92% identical), RNU6-49P (92% identical), RNU6-1 (91% identical), and 1283 more.